TOX3 (TOX high mobility group box family member 3)
Diseases named in the same sentence as TOX3 in open-access papers (continued):
Sharing a sentence is not in itself a finding about the gene and the disease.
breast carcinoma (continued). "The same study described a FOXA1 binding site at breast cancer SNP rs4784227, whose risk allele segregates with the risk allele of rs3803662; FOXA1 preferentially bound the site that included the rs4784227 risk allele resulting in a 5-fold decrease in TOX3 expression." (PMID 23270421, 2012). "Similar patterns were observed for SNPs rs3803662 in TOX3/TNRC9 and rs4973768 in SLC4A7/NEK10 in which the associations were predominantly with ER-positive breast cancer for both BRCA1 and BRCA2 mutation carriers, in line with results from studies of breast cancer in the general population." (PMID 22053997, 2011). "Previous studies have assessed whether SNP associations with breast cancer vary with ER status: rs2981582 (in FGFR2), rs3803662 in (TOX3), rs13387042 (in 2q35), and rs13281615 (in 8q24) were more strongly associated with ER-positive disease than ER-negative disease." (PMID 22087758, 2011). "According to the previously published literature, TOX3 can change the methylation status of its promoter and reduce the expression level of BRCA1, thus potentiating the growth and metastasis of breast cancer." (PMID 38463397, 2024). "In fact, both SConES GS and GM selected chromosome regions related to breast cancer, like 3p24 (SLC4A7/NEK10), 5p12 (FGF10, MRPS30), 10q26 (FGFR2), and 16q12 (TOX3)." (PMID 33735170, 2021). "FOXA1 is thought to be a positive regulator of TOX3 expression, mediated by binding to an upstream enhancer, and knockdown of FOXA1 in a breast cancer cell line decreased TOX3 expression." (PMID 25632947, 2015). "The results suggest that the effect of the risk allele of rs3803662 is strongest in luminal A tumours and that the expression levels of TOX3 and/or LOC643714 affect the progression of breast cancer." (PMID 23270421, 2012). "Although further analysis is needed, we conclude that genotype at rs3803662 and expression of TOX3 and LOC643714 have adverse effect on breast cancer prognosis." (PMID 23270421, 2012). "It is unclear what the function of the TNRc9 (also known as TOX3) gene is; however, it contains a putative high mobility group box motif which suggests that it may act as a transcription factor and this gene has been implicated in breast cancer metastasis to the bone." (PMID 18681954, 2008). "The genes FGFR2, CCND1 and TOX3 are still not studied much in relation to the roles in breast cancer although genetic studies have suggested their involvement in cancer risk." (PMID 35267517, 2022). "In this study, we showed that BMP6 was upregulated by TOX3 in KGN cells, which may contribute to the understanding of the roles of TOX3 and BMP6 in the pathogenesis of breast cancer." (PMID 33716953, 2020). "Only SNPs in the known breast cancer susceptibility loci FGFR2 and TOX3 were associated with non-TN breast cancer in BRCA2 carriers, and none were associated with TN breast cancer at P <10−6." (PMID 25919761, 2014). "In this regard, the differential methylation of TOX and TOX3 between lung and breast cancer, TOX2 across cigarette smoking habit, and TOX3 by the histology of lung cancer suggest, methylation of TOX subfamily genes could be important biomarkers for cancer profiling." (PMID 22496870, 2012). "To showcase our method, we evaluate associations between breast cancer susceptibility and SNPs in estrogen receptor alpha (ESR1), fibroblast growth factor receptor 2 (FGFR2), RAD51 homolog B (RAD51B), and TOX high mobility group box family member 3 (TOX3) genes, without access to raw genotype data." (PMID 32287273, 2020). "However, not much is known of the role of TOX3 itself in breast cancer biology." (PMID 24069272, 2013).
breast carcinoma (continued). "On the other hand, some reports suggest that variation in FGFR2, TOX3, HCN1, and at 2q35 may be more strongly associated with estrogen receptor-positive cancers, but mammographic density has not been found to be differentially related to breast cancers by steroid receptor status." (PMID 19232126, 2009). "To address whether the induction of TFF1 by TOX3 was ER-dependent, we transfected triple negative basal MDA-MB-231 breast cancer cells, which do not express ER or TOX3." (PMID 25632947, 2015).
breast tumors (11 papers, 2010 to 2020). "Through TCGA dataset, we confirmed that rs3803662 and rs4784227 are associated with TOX3 expression in breast tumors." (PMID 27806084, 2016). "The molecular subtype-specific expression of TOX3 in breast tumors is significantly associated with epigenetic modifications at CpG islands of the promoter." (PMID 27806084, 2016). "We tested the possibility by performing mQTL between the SNP variants and TOX3 promoter methylation in breast tumors." (PMID 27806084, 2016). "Expression quantitative trait loci (eQTL) analyses revealed significant associations of rs3803662 and rs4784227 genotypes with TOX3 expression in breast tumors." (PMID 27806084, 2016). "Germline genotypes also contribute to TOX3 expression with a significant association of rs3803662 and rs4784227 with TOX3 expression in breast tumors." (PMID 27806084, 2016). "TOX3 risk-allele carriers have been reported to develop more lobular breast tumors, and patients with this SNP who develop luminal A (LumA) breast tumors have shorter overall survival." (PMID 25632947, 2015). "In our study, we found a frequency of 4.5% coding TOX3 mutations in primary breast tumours, clustered in exon 3 and in exon 7 (the latter contains the trinucleotide repeat region)." (PMID 24069272, 2013). "We screened TOX3 for mutations in 133 breast tumours and identified four mutations (three missense, one in-frame deletion of 30 base pairs) in six primary tumours, corresponding to an overall mutation frequency of 4.5%." (PMID 24069272, 2013). "A correlation of the rs3803662 genotype with lower TOX3 mRNA has been observed in breast tumours where TOX3 mRNA expression decreased in an allele-dependent manner." (PMID 23270421, 2012). "Thus, our data support a plausible molecular mechanism integrating epigenetic modifications of the TOX3 promoter and allele specific expression of SNPs in aggressive behavior of luminal breast tumors with high TOX3 expression." (PMID 27806084, 2016). "TOX3 mutations were also found in breast tumors with an overall mutation frequency of 4.5%." (PMID 27806084, 2016). "In conclusion, our study reveals that TOX3 is mutated in breast tumours, albeit at a low frequency." (PMID 24069272, 2013). "In addition to the previous functional study of risk variants, we investigated epigenetic regulation of TOX3 expression on breast tumors in silico, revealing an inverse correlation between subtype-specific expression of TOX3 and CpG site methylation of the promoter." (PMID 27806084, 2016). "In addition, rare mutations of TOX3 in breast tumors have been reported." (PMID 25632947, 2015). "TOX3 has been reported to be highly expressed in breast tumors and is closely related to estrogen receptors." (PMID 33716953, 2020). "To validate CpG site methylation of TOX3 in a large set of breast tumors, we analyzed methylation levels of the four CpG dinucleotides using the TCGA HumanMethylation450 Array data." (PMID 27806084, 2016). "We next examined TOX3 CNV in a large set of breast tumors using TCGA GISTIC2 CNV dataset and demonstrated similar levels of copy numbers across different subtypes with slightly lower levels in luminal tumors." (PMID 27806084, 2016). "TCGA dataset verified significantly lower levels of methylation of the promoter in luminal breast tumors with an inverse correlation between methylation and expression of TOX3." (PMID 27806084, 2016). "One-way ANOVA and Tukey’s multiple comparison tests at the four CpG islands showed significantly lower methylation in the CpG islands of the TOX3 promoter in luminal A and B breast tumors compared to normal breast tissues and basal-like breast tumors." (PMID 27806084, 2016). "To validate TOX3 expression in a large set of primary breast tumors, we analyzed three datasets, TCGA, the University of North Carolina (UNC), and University of Chicago (U of C)." (PMID 27806084, 2016).
breast tumors (continued). "In this study, we investigated both genetic and epigenetic factors contributing to TOX3 expression in breast tumors and cell lines." (PMID 27806084, 2016). "To study the expression of this nuclear protein in human mammary glands and breast tumors, we generated a rabbit monoclonal antibody specific for human TOX3." (PMID 25632947, 2015). "To assess expression of the TOX3 protein in breast tumors, we stained a tissue array with AJ-33 antibody." (PMID 25632947, 2015). "Among primary tumors, TOX and TOX3 were methylated in 5% (9/190) and 58% (110/190) lung and 43% (34/80) and 30% (24/80) breast tumors, respectively." (PMID 22496870, 2012). "TOX3 is often amplified and overexpressed in breast tumors, particularly in advanced breast tumors." (PMID 27806084, 2016). "Gene expression data from microarrays were available for TOX3 in 160 breast tumours." (PMID 23270421, 2012). "Although more mechanical studies are required to determine the regulation of TOX3 expression by epigenetic modifiers, our findings on the upregulation of TOX3 by cytosine methylation raise the possibility of new epigenetic biomarkers for prognosis of aggressive ER positive breast tumors." (PMID 27806084, 2016). "Nevertheless, this study also reports genomic amplification of TOX3 in advanced breast tumours, which we did not detect in our own samples." (PMID 24069272, 2013). "A decrease in TOX3 mRNA according to the rs3803662 genotype was observed in a large Dutch study of 1401 breast tumours but analysis according to ER status was not reported." (PMID 23270421, 2012).
lung carcinoma (9 papers, 2008 to 2024). "Second, the subjects of the study were recruited only from Southwestern China, large-scale studies are required to clarify the association of the SNPs at the TOX3/LOC643714 locus with lung cancer risk in the other Han Chinese populations." (PMID 27486757, 2016). "The genotyping data demonstrated that three SNPs (rs9933638, rs12443621, and rs3104746) at the TOX3/LOC643714 locus were associated with elevated risk of lung cancer and might be potentially biologically relevant to lung carcinogenesis." (PMID 27486757, 2016). "Moreover, TOX3 can also strengthen the metastatic ability of lung cancer cells through regulating EMT and Hippo‐related signaling pathways." (PMID 38463397, 2024). "First, environmental lighting conditions may influence the secretion of melatonin, which can inhibit lung cancer cell migration and proliferation by decreasing TOX3 expression through the direct activation of miR-135b-3p." (PMID 37726707, 2023). "Interestingly, the prevalence for TOX3 methylation among lung cancer patients was significantly greater in squamous cell carcinoma 79% (15/19) compared to adenocarcinoma 56% (95/171)." (PMID 22496870, 2012). "To further investigate the role of TOX3 and SPDEF expression in cancer progression, we performed a survival curve analysis to evaluate the effects of gene expression in lung cancer patients with lung adenocarcinoma." (PMID 29285217, 2017). "BICD2, CDA, NMNAT2, SERPINB13, and TOX3 have no specificity to either AC or SCC but to lung cancer." (PMID 19761563, 2009).
Anxiety (3 papers, 2020 to 2023). Intense feelings of nervousness, tension, or panic often arise in response to interpersonal stresses. "Recently an abstract reported that Tox3 knockout rats present an obesity phenotype, male and female sterility, and a behavioral phenotype (increased anxiety)." (PMID 32425888, 2020). "Additionally, rats with global lower levels for Tox3 display obesity, sterility (male and female) and increased anxiety, all of which are symptoms of PCOS." (PMID 36794750, 2023).
colorectal cancer (3 papers, 2021 to 2024). A primary or metastatic malignant neoplasm that affects the colon or rectum. "Besides, research found TOX3 may play a vital part in the prognosis and treatment of gastric cancer as well as be a therapeutic target for clear renal cell carcinoma and colorectal cancer." (PMID 34976002, 2021).
Insulin resistance (3 papers, 2020 to 2025). Increased resistance towards insulin, that is, diminished effectiveness of insulin in reducing blood glucose levels. "The phenotype–genotype study showed that susceptibility variants in THADA and INSR conferred risk for metabolic syndrome, and variants of DENND1A and TOX3 were associated with insulin resistance in PCOS women." (PMID 36836035, 2023). "TOX3 overexpression activates the gluconeogenic program, resulting in hyperglycemia and insulin resistance in mice and hepatocyte-specific TOX3 knockout suppresses gluconeogenesis through FOXO1." (PMID 40218365, 2025). "PCOS susceptibility variants in THADA and INSR are associated with metabolic syndrome and variants in TOX3 and DENND1A are associated with insulin resistance." (PMID 32425888, 2020). "INSR and TOX3 are significantly correlated to insulin resistance or metabolic syndrome." (PMID 36836035, 2023). "This genotype-phenotype study provides clues that THADA, INSR, TOX3, and DENND1A play important role in the etiology of PCOS, possibly through insulin resistance and metabolic disorder related pathways." (PMID 32425888, 2020).
lung adenocarcinoma (3 papers, 2017 to 2024). A carcinoma that arises from the lung and is characterized by the presence of malignant glandular epithelial cells. "In our study, TOX3 was significantly upregulated in lung adenocarcinoma, and higher expression of TOX3 is correlated with better survival outcome." (PMID 29285217, 2017). "The results showed that the mRNA expression of either TOX3 or SPDEF is upregulated in lung adenocarcinoma." (PMID 29285217, 2017). "The results showed that both TOX3 and SPDEF are significantly upregulated in lung adenocarcinoma, compared to normal tissue." (PMID 29285217, 2017). "The prognostic values of TOX3 and SPDEF expression in lung adenocarcinoma were shown as forest plots, which were derived from the PrognoScan database with a Cox p-value < 0.05, and the Kaplan–Meier plotter database with a log-rank p-value < 0.05." (PMID 29285217, 2017).
polycystic ovary syndrome (3 papers, 2021 to 2023). A disorder that manifests as multiple cysts on the ovaries. "Human DNA variants in the TOX3 locus have been associated with polycystic ovarian syndrome (PCOS) in several populations." (PMID 36794750, 2023).
diabetes (2 papers, 2018 to 2020). "After exclusion of PCOS cases with a family history of diabetes, hypertension, or dyslipidemia, the phenotype-genotype correlations between the genes INSR and TOX3 and MS or IR were still significant (P < 0.05)." (PMID 32425888, 2020).
gastric cancer (2 papers, 2013 to 2021). A primary or metastatic malignant neoplasm involving the stomach. "The associations of TOX3 rs3803662 genotypes with gastric cancer survival in different genetic models were assessed by Cox regression analyses." (PMID 24069142, 2013). "An association of genetic variation in TOX3 with gastric cancer survival was conducted in our study." (PMID 24069142, 2013). "Association between TOX3 rs3803662 polymorphism and gastric cancer patients' survival." (PMID 24069142, 2013). "If validated in further research, TOX3 rs3803662 might also be taken as potential genetic marker for gastric cancer susceptibility except for prognosis." (PMID 24069142, 2013). "We hypothesize that TOX3 rs3803662 is associated with gastric cancer survival in a Chinese population, which can be identified as an independent prognostic marker of gastric cancer survival." (PMID 24069142, 2013). "In our present study, we investigated the effect of TOX3 rs3803662 on survival of gastric cancer patients." (PMID 24069142, 2013). "In conclusion, TOX3 rs3803662 plays an important role in the survival of gastric cancer patients, especially can be considered as an independent prognostic marker of diffuse-type gastric cancer." (PMID 24069142, 2013). "TOX3 rs3803662 might play an important role in the prognostic outcome and treatment of gastric cancer, especially perhaps further help in explaining the reduced risk of death associated with diffuse-type gastric cancer." (PMID 24069142, 2013).
glioma (2 papers, 2020 to 2021). A benign or malignant brain and spinal cord tumor that arises from glial cells (astrocytes, oligodendrocytes, ependymal cells). "The involvement of Nestin in GBM and its use as a biomarker for glioma stem cells suggests a possible interaction of TOX3 in this cancer." (PMID 34298641, 2021). "The analysis of TOX protein family members showed coexpression of TOX, TOX2, TOX3, and TOX4 in pan-glioma analysis, LGG alone, and GBM alone." (PMID 32762688, 2020).
invasive breast carcinoma (2 papers, 2012 to 2021). A carcinoma that infiltrates the breast parenchyma. "Most recently, replication of two index SNPs: rs3803662 at 16q12.2/TOX3 and rs10941679 at 5p12 near MRPS30 involving 7,800 African American women (including 316 women with incident invasive breast cancer) have also been established." (PMID 22778704, 2012).
lymph node metastasis (2 papers, 2013 to 2023). "TOX3 rs3803662 was investigated with survival of diffuse-type gastric cancer patients by stratified analysis of tumor size, histology, depth of invasion, lymph node metastasis, distant metastasis, TNM stage, drinking status, and tumor site." (PMID 24069142, 2013). "The increased TOX3, WDR5, and ABCG2 expression was respectively detected in the majority of metastatic CRCs as compared with those with no lymph node metastasis." (PMID 37708089, 2023).
mediastinal tumours (2 papers, 2024 to 2025). "HN-PG and the suspected non-chromaffin mediastinal tumours had low expression of the chromaffin cell marker CARTPT24, neural transcriptional regulators (TFAP2B, TOX3, GATA3, POU4F, NEUROG2, PAX2), HOX genes (HOXA1-10, HOXB4, HOXB6-9, HOXC4-HOXC13), and the long non-coding RNA HOTAIR." (PMID 40097403, 2025). "HN-PG and the suspected non-chromaffin mediastinal tumours had low expression of the chromaffin cell marker CARTP24, neural transcriptional regulators (TFAP2B, TOX3, GATA3, POU4F, NEUROG2, PAX2), HOX genes (HOXA1–10, HOXB4, HOXB6–9, HOXC4-HOXC13), and the long non-coding RNA HOTAIR." (PMID 38978571, 2024).
migraine (2 papers, 2020 to 2022). "Previous GWASs have identified six RLS risk loci (MEIS1, BTBD9, MAP2K5, PTPRD, TOX3, and an intergenic region on chromosome 2p14); however, only MEIS1 has been found to be associated with RLS in patients with migraine via candidate gene approach." (PMID 35350973, 2022).
non-small cell lung carcinoma (2 papers, 2024 to 2025). A group of at least three distinct histological types of lung cancer, including non-small cell squamous cell carcinoma, adenocarcinoma, and large cell carcinoma. "Melatonin reduces the expression of circ_0017109 by directly activating miR-135b-3p to downregulate TOX3 expression and inhibit the proliferation of non-small cell lung cancer cells." (PMID 40756978, 2025).
acute myeloid leukemia (1 paper, 2023). Acute myeloid leukemia (AML) is a group of neoplasms arising from precursor cells committed to the myeloid cell-line differentiation. "A decrease in TOX3 expression has been noted in cases of acute myeloid leukemia (AML)." (PMID 38020130, 2023).